ERAS (ES cell expressed Ras)
Diseases named in the same sentence as ERAS in open-access papers:
ERAS is named in the same sentence as 24 diseases in open-access papers, as found by Europe PMC text mining. Sharing a sentence is not in itself a finding about the gene and the disease. The quoted sentences say what the papers report.
gastric cancer (7 papers, 2013 to 2025). A primary or metastatic malignant neoplasm involving the stomach. "Recent studies have demonstrated that ERas plays a critical role in the occurrence and progression of many malignant tumors, such as gastric cancer, breast cancer, and neuroblastoma." (PMID 32700262, 2020). "Previous studies have shown that ERas is pivotal in the occurrence and development of various malignant tumors, especially gastric cancer." (PMID 32700262, 2020). "A previous study showed that ERas was strongly expressed in 142 gastric cancer tissues and closely related to liver or lymph node metastases." (PMID 32700262, 2020). "Increased ERAS expression is also observed in human gastric carcinoma and neuroblastoma cells, and its expression is significantly associated with metastasis to the lymph nodes and liver." (PMID 26269429, 2015). "ERAS is also expressed in human gastric cancer, where it may play a crucial role in gastric cancer cell survival and metastasis to the liver via downregulation of E-cadherin." (PMID 35685342, 2022).
breast cancer (3 papers, 2018 to 2021). A primary or metastatic malignant neoplasm involving the breast. "Although it is possible that the inappropriate expression of ERAS in human breast tumors is a consequence of tumor development, our finding that ERAS expression causes mammary tumors in mice strongly argues in favor of an oncogenic role in humans." (PMID 34771750, 2021). "It is thus noteworthy that ERAS expression causes, above all, mammary tumors, even in male mice." (PMID 34771750, 2021). "ERAS, as many other genes important in early development, seems to be implicated in cancer, as it is expressed in some cell lines derived from gastric, colorectal, pancreatic and breast cancers, as well as in neuroblastomas." (PMID 34771750, 2021). "Our results clearly demonstrate that ERAS is a true oncogene able to produce mammary tumors when inappropriately expressed." (PMID 34771750, 2021). "Mice expressing ERAS in myoepithelial mammary cells developed mammary tumors with a high incidence and multiplicity." (PMID 34771750, 2021). "We then addressed the biological significance of ERAS in an additional human breast cancer series, a cohort of formalin‐embedded grade 3 infiltrative ductal breast carcinomas (see45 for clinical and molecular description of the tumor series)." (PMID 30158566, 2018). "We analyzed ERAS expression in human breast tumors using data from The Cancer Genome Atlas (TCGA) breast cancer dataset." (PMID 30158566, 2018). "Therefore, ERAS has a strong transforming ability, being able to produce mammary tumors in the small rudiment of mammary tissue present in male mammary glands." (PMID 34771750, 2021). "Normally, ERas is not expressed in somatic cells because of epigenetic transcriptional silencing, but many studies have found that ERas expression exists in GC tissue and several cancer cell lines, including breast cancer, colorectal cancer, and pancreatic cancer." (PMID 32083074, 2019). "In this manuscript, we have analyzed and characterized mouse mammary tumors generated by random Sleeping Beauty transposon mutagenesis and identify ERAS -a member of the RAS family silenced in adult tissues- as a new gene involved in progression and malignancy of breast cancer." (PMID 30158566, 2018). "ERAS is a constitutively active RAS protein that is not expressed in adult tissues, and given that it seemed to act as a tumor driver in mouse, we decided to study the effect of the expression of ERAS in human mammary gland cells and its relation to breast cancer." (PMID 30158566, 2018). "ERas mRNA is expressed in several cancer cell lines, including colorectal carcinomas, pancreatic carcinomas, and breast carcinomas, but not in normal cell lines." (PMID 32083074, 2019).
pancreatic cancer (3 papers, 2019 to 2023). "It is worth mentioning that we also found ERas was involve in the distant metastases, suggesting that ERas may serve as a potential diagnostic marker in pancreatic cancer." (PMID 32700262, 2020). "ERas was activated in pancreatic cancer cells, where ERas plays a critical role in PCCs survival and EMT." (PMID 32700262, 2020). "In our study, we revealed that ERas is highly expressed in pancreatic cancer and exerted tumor-promoting effects." (PMID 32700262, 2020). "Knockdown of ERas in pancreatic cancer cells by siRNA significantly decreased cell proliferation, colony formation, migration, and invasion and promoted cell apoptosis in vitro." (PMID 32700262, 2020). "Taken together, these data suggest that ERas promotes pancreatic cancer cell migration, invasion, and EMT." (PMID 32700262, 2020). "In this study, we found that ERas mRNA and protein were upregulated in pancreatic cancer tissues and cells compared with controls." (PMID 32700262, 2020). "In this study, we not only identified the expression of ERas in pancreatic cancer cells, but also elucidated the role and potential mechanisms of ERas in pancreatic cancer." (PMID 32700262, 2020). "We observed a significant decrease in N-cadherin expression in pancreatic cancer cells in response to ERas gene silencing by immunofluorescence assay and western blot." (PMID 32700262, 2020). "To ascertain the molecular mechanisms by which ERas promotes pancreatic cancer progression, we examined several signaling transduction pathways that might be crucial in tumorigenesis and Erk and Akt were focused on in the following experiments." (PMID 32700262, 2020). "We next examined the effect of ERas on pancreatic cancer pathogenesis." (PMID 32700262, 2020). "We then explored the role of ERas in pancreatic cancer tumor progression in vivo." (PMID 32700262, 2020). "Our data suggest that targeting ERas and its relevant signaling pathways might represent a novel therapeutic approach for the treatment of pancreatic cancer." (PMID 32700262, 2020). "In conclusion, we confirmed that ERas was overexpressed in pancreatic cancer tissues and PCCs." (PMID 32700262, 2020). "In addition, we revealed the biological role and potential signal pathways of ERas in pancreatic cancer progression." (PMID 32700262, 2020). "ERas may exert its function in pancreatic cancer by activating and regulating various downstream signaling transduction pathways." (PMID 32700262, 2020). "Activation of signaling cascades by ERas may significantly enhance pancreatic cancer cells proliferation, migration, and colony formation ability and inhibit apoptosis." (PMID 32700262, 2020). "We further investigated the regulatory mechanisms of ERas in pancreatic cancer and found that ERas may activate the Erk/Akt signaling pathway." (PMID 32700262, 2020). "Furthermore, tumor growth and EMT were inhibited in xenografts derived from pancreatic cancer cells with ERas downregulation." (PMID 32700262, 2020). "However, the expression and function of ERas, a member of the Ras family, in pancreatic cancer have been unknown." (PMID 32700262, 2020). "Together, these findings suggest that ERas may potentiate the activities of pancreatic cancer cells through the Erk and Akt pathway, suggesting that these pathways may represent a suitable target for the therapeutic treatment of pancreatic cancer." (PMID 32700262, 2020). "Thus, ERas may act as a novel tumor-promoting factor and play a critical role in pancreatic cancer development." (PMID 32700262, 2020). "Both ERas mRNA and protein expression were detected in all five pancreatic cancer cell lines, while no expression was detected in the HPDE cell line." (PMID 32700262, 2020). "To determine whether ERas is involved in the development of pancreatic cancer, we first analyzed ERas mRNA and protein expression in HPDE and pancreatic cancer cell lines by real-time PCR and western blot analysis." (PMID 32700262, 2020).
pancreatic cancer (continued). "However, the expression and potential role of ERas in pancreatic cancer have not been investigated." (PMID 32700262, 2020).
breast tumors (2 papers, 2018 to 2021). "Immunohistochemical, RT-qPCR and bioinformatics analysis of human samples show that ERAS is aberrantly expressed in 8–10% of breast tumors and this expression is associated with distant metastasis and reduced metastasis-free survival." (PMID 30158566, 2018). "Analysis of normal and tumoral breast samples from this dataset showed that approximately 8% of breast tumors express ERAS, although at low levels." (PMID 30158566, 2018). "Nonetheless, our data suggest that ERAS expression tends to occur in tumors with luminal phenotype and distant metastases, supporting the idea of ERAS having a role in breast tumor malignancy." (PMID 30158566, 2018). "In this respect, metformin has been shown to induce the expression of miR-200c56, suggesting a way for the specific therapeutic treatment of ERAS-expressing breast tumors." (PMID 30158566, 2018). "In a collection of 32 human breast tumors, we found unequivocal expression of ERAS at the mRNA and protein levels." (PMID 30158566, 2018). "Here, we describe the expression of ERAS in a small subset of breast tumors." (PMID 30158566, 2018). "In summary, our results reveal that inappropriate activation of ERAS may be important in the development of a subset of breast tumors." (PMID 30158566, 2018). "In addition, the analysis of ERAS expression data from TCGA also suggests that a low percentage of breast tumors express ERAS, and immunohistochemical analysis of a grade 3 breast tumor tissue microarray confirmed that ERAS is aberrantly expressed in less than 10% of tumors." (PMID 30158566, 2018). "These epigenetic modifications are not unexpected: ERAS is localized in the X chromosome, and abnormalities in this chromosome are common in breast tumors." (PMID 30158566, 2018). "In fact, preliminary studies from our laboratory (not shown) also suggest that ERAS activation in breast tumors could be mediated by epigenetic processes." (PMID 30158566, 2018).
colon cancer (2 papers, 2021 to 2024). "For example, a novel fusion oncoprotein which could promote AKT signaling activity, ubiquitin specific peptidase 9 X-linked-ES cell expressed Ras (USP9X-ERAS), is formed by chromothripsis involving the US9PX and ERAS genes in colon cancer cells." (PMID 38553459, 2024). "Finally, in patients with primary colon cancer gene fusions between USP9X and ERAS have been found, resulting in the constitutive expression of relatively high levels of ERAS." (PMID 34771750, 2021).
melanoma (2 papers, 2021 to 2023). A malignant, usually aggressive tumor composed of atypical, neoplastic melanocytes. "So, in murine mutagenesis experiments using the Sleeping Beauty transposon, which result in mammary gland tumors, melanoma and metastatic medulloblastoma, ERAS emerges as a candidate oncogene." (PMID 34771750, 2021). "A study using SB insertional mutagenesis in mice conditionally expressing Braf (V618E) identifies drivers of melanoma formation and mediators of resistance to the BRAF inhibitor plx4720, including Braf, Mitf, and ERas (ES-cell expressed Ras)." (PMID 38098473, 2023).
asthma (1 paper, 2015). "Although ERAS was one of the genes indicating association with aspirin-induced asthma in our study, there are only single data supporting its role." (PMID 26646719, 2015). "This pilot study implies a positive association between CNPY3, ERAS, FOSL1 and aspirin-intolerant asthma, suggesting that these findings would be useful for further investigations of NSAIDs mechanism." (PMID 26646719, 2015).
bladder cancer (1 paper, 2022). "ERAS was found to be constitutively expressed in bovine placental tissue and ERAS overexpression was detected in naturally occurring bladder cancer of cattle associated with bovine papillomavirus (BPV) infection." (PMID 35685342, 2022).
bladder tumors (1 paper, 2022). "It is worth remembering that ERAS has been shown to be involved both in mitophagy mediated by parkin and receptors in naturally occurring papillomavirus-associated bladder tumors in cattle." (PMID 35685342, 2022).
neuroblastoma (1 paper, 2015). Neuroblastoma (NB) is the most common solid, extracranial childhood tumor. "Neuroblastoma cells transfected with ERAS expression vector showed resistance to chemotherapeutic agents and promotion of transforming activity." (PMID 26269429, 2015).
overgrowth syndrome (1 paper, 2021). A group of syndromes caused by genetic birth defects that may lead to the development of malignancies. "In spite of the low level of ERAS expression, these transgenic mice showed phenotypic alterations resembling overgrowth syndromes caused by the activation of the AKT-PI3K pathway." (PMID 34771750, 2021). "In this context, ERAS adds up to the list of genes whose mutation can lead to overgrowth syndromes (as AKT, PIK3CA, PTEN) or RASopathies (as H-RAS, RASA1, NF1 and RAF1, among others)." (PMID 34771750, 2021). "The results reported here demonstrate that ERAS acts as a true oncogene in mammary glands and suggest that ERAS could be implicated in any of the RASopathies and/or overgrowth syndromes of unknown genetic origin." (PMID 34771750, 2021).
rectal cancer (1 paper, 2014). A primary or metastatic malignant neoplasm that affects the rectum. "Notably, many of these genes (ADRA1A, BARHL2, ERAS, ESRRG, RNF220 and ST6GALNAC5) are also targets of the Polycomb Repressor Complex-2, further supporting an important role of epigenetic crosstalk in controlling rectal cancer therapeutic responsiveness." (PMID 25261372, 2014).
sarcoma (1 paper, 2020). A usually aggressive malignant neoplasm of the soft tissue or bone. "In this study, the expression of YWHAE-NTRK3 induced sarcomas at 40% penetrance, whereas that of four other fusions, namely PPFIBP1-NTRK3, PAK2-RAF1, GAB1-ABL1 and wild-type ERAS, did not." (PMID 32825119, 2020).
teratoma (1 paper, 2018). A non-seminomatous germ cell tumor characterized by the presence of various tissues which correspond to the different germinal layers (endoderm, mesoderm, and ectoderm). "EpCAM and ERas interaction was subsequently validated in independent co-immunoprecipitations of lysates from YFP- and EpCAM-YFP-expressing F9 teratoma cells and E14TG2α ESC." (PMID 29379062, 2018).
viral infections (1 paper, 2022). "Furthermore, ERAS may be an important factor of both parkin-dependent and parkin-independent activated mitophagy in viral infections." (PMID 35685342, 2022).
cancer (11 papers, 2013 to 2025). A tumor composed of atypical neoplastic, often pleomorphic cells that invade other tissues. "In MCF10A cells, we have seen that ERAS downregulates miR-205, miR-141 and miR-200c; these are tumor suppressor miRNAs whose reduced expression has been consistently associated to cell growth, invasion, migration, cancer stem cells, EMT and breast cancer." (PMID 30158566, 2018). "ERAS expression has been found in certain human cancers, including colorectal, pancreatic, neuroblastoma, and breast carcinoma cell lines, as well as in mouse mammary tumors." (PMID 35685342, 2022). "ERas, a novel Ras family member, was first identified in murine embryonic stem cells and is upregulated in various cancers." (PMID 32700262, 2020). "Six of these positive tumors were classified with a luminal A phenotype, two were luminal B and two were basal-like, which suggests that carcinomas with overexpression of ERAS mainly are luminal tumors." (PMID 30158566, 2018). "To date, there are few studies on the relationship between ERas and cancer, and the function of ERas has yet to be determined." (PMID 23612786, 2013). "It has been suggested that ERAS coordinates cell proliferation and cell differentiation, plays a central role in the stimulation of somatic cell reprogramming, which is similar to the cancer initiation process." (PMID 35685342, 2022). "ERAS may be involved in the pathogenesis and chemotherapy resistance of some types of cancers." (PMID 31781628, 2019). "Thus, ERAS may be an important regulator for some types of human cancer." (PMID 26269429, 2015). "Although ERAS is overexpressed in some tumoral samples and in several cancer cell lines of human origin, it is not known if its expression drives tumor formation or if, alternatively, its expression is a secondary event in tumoral transformation." (PMID 34771750, 2021).
tumor (7 papers, 2013 to 2022). "Decreased tumor volumes and weights were found in the ERas downregulation group compared with the control group." (PMID 32700262, 2020). "TUNEL assays also showed increased apoptotic cells in ERas knockdown xenograft tumors, suggesting ERas inhibits the apoptosis of tumor cells in vivo." (PMID 32700262, 2020). "RT-qPCR analysis showed that one tumor (T20) presented high levels of ERAS mRNA, while the rest of the tumors produced null or background signals." (PMID 30158566, 2018). "To evaluate the roles of ARF activation and ERAS disruption in tumour resistance in NMR-iPSCs, we introduced short hairpin RNAs targeting ARF (shARF) and/or Ms-ERas (mERas) into NMR-iPSCs (shARF-, mERas- or shARF/mERas-NMR-iPSCs)." (PMID 27161380, 2016). "Although there are several reports showing ERAS expression in tumoral cell lines and human tumor samples, it is unknown if ERAS deregulated expression is enough to drive tumor development." (PMID 34771750, 2021). "We studied whether ERAS expression renders the mice more prone to tumor development, with a special emphasis in mammary glands." (PMID 34771750, 2021). "Importantly, subcutaneous tumor growth was inhibited in xenografts derived from cells with ERas knockdown." (PMID 32700262, 2020). "Thus, ERAS promotes tumor progression, invasion and dedifferentiation of MDA-MB-231 cells and increases the metastatic capacity of this cell line." (PMID 30158566, 2018). "Thus, NMR-specific ARF regulation and the disruption of ERAS regulate tumour resistance in NMR-iPSCs." (PMID 27161380, 2016). "Since ERas plays an important role in tumor-like growth of ES cells subcutaneously injected into nude mice, we hypothesized that ERas plays a role in tumor proliferation." (PMID 23612786, 2013). "Therefore, ERas is confirmed to be an important gene in affecting tumor proliferation and metastasis." (PMID 23612786, 2013). "In addition, we also show that ERAS increases tumor growth and metastasis in MBA-MD-231 cells." (PMID 30158566, 2018). "Thus, ARF activation and disruption of ERAS regulates the tumour resistance of NMR-iPSCs." (PMID 27161380, 2016). "We conclude that the tumour resistance in NMR-iPSCs is based on NMR-specific ARF regulation and disruption of ERAS." (PMID 27161380, 2016). "Immunohistochemistry confirmed that tumor T20, a high-grade (G3), luminal B/Her2 type tumor was positive for ERAS antibody staining whereas all other tumors were negative." (PMID 30158566, 2018). "Thus, the study of ERAS expression in this particular human tumor type would be of great interest, but this is a rare tumor type, and it is not easy to obtain samples." (PMID 34771750, 2021). "Collectively, these results suggest that ERAS expression in human non-tumorigenic mammary cells leads to a marked EMT process and increases the number of cells expressing markers characteristic of mammary stem and tumor cells." (PMID 30158566, 2018).
infection (1 paper, 2020). The state of being infected such as from the introduction of a foreign agent such as serum, vaccine, antigenic substance or organism. "Furthermore, PHB2 co-precipitated ERAS more appreciably in cells from bladder mucosa infected by BPVs rather than in cells from healthy mucosa, which suggested that this functional stochiometric complex was upregulated in activated mitophagy upon BPV infection." (PMID 32751272, 2020).
ERAS also shares sentences with these, for which no sentence is quoted: breast (1 paper); colorectal cancer (1); ductal breast carcinomas (1); onychogryphosis (1); RASopathies (1); teratocarcinoma (1).